TGFB1 (transforming growth factor beta 1)
Diseases named in the same sentence as TGFB1 in open-access papers (continued):
Sharing a sentence is not in itself a finding about the gene and the disease.
cancer (continued). "Moreover, ITGAV knockdown in EpCAM+ plastic cancer cells significantly reduced EMT induction in response to TGFβ and blocked the generation of mesenchymal EpCAMneg cancer cells, although cancer cells showed pSMAD3 induction upon TGFβ1 treatment and translocation of pSMAD2 to the nucleus." (PMID 39075581, 2024). "Importantly, our results are supported by the hypothesis that NDRG1 has a different interplay with the same molecules in distinct cancers and cell types 8, namely TGFβ1, GSK3β, and NF-κB." (PMID 36594086, 2023). "Also, since TGF-β1 is a strong immunosuppressor, existing data suggests that TGFβ1-inhibitory therapies could restore cancer immunity and even synergize with other immunotherapies." (PMID 37925591, 2023). "Additionally, TGFB1/TGFBR1 exhibited positive correlations with CILP2 in nearly all cancer types." (PMID 38136386, 2023). "Notably, TGFB1 turned out to be an adverse prognosticator of OS for all three cancers." (PMID 37925591, 2023). "Also, we suggest that once cancer cells have escaped from their primary site and reached distant organs, short exposure to TGFβ1 would be enough to activate NDRG1 and EMT, facilitate colonization, cell proliferation, and chemoresistance by controlling the homeostasis of ALDH1+." (PMID 36594086, 2023). "Furthermore, stimulating ECs with JAG1 expressed on cancer cells could increase the expansion and differentiation of T-reg by up-regulating TGFB1." (PMID 35673567, 2022). "We also found that AP3S1 expression significantly and positively correlated with TGFB1 and IL-10 expression in pan-cancer, which in turn were significantly correlated with TAMs/CAFs, and we speculate that this may be a potential mechanism by which AP3S1 affects infiltration of TAMs/CAFs." (PMID 35874816, 2022). "Therefore, we hypothesized that CP treatment would reduce TGFβ1 expression and enhance T-cell-mediated tumoricidal effects, improving the effectiveness of immune checkpoint therapies in cancer treatment." (PMID 36209170, 2022). "The CAFDL signature was significantly positively associated with TGFB1, CD276, CD40, VEGFA, VEGFB, etc., but showed significantly negative correlation with immune checkpoints (such as CD274, PDCD1, CTLA4, TIGHT, and HAVCR2) and anti-cancer immune regulators (IFNG, IDO1, and GZMA)." (PMID 35967425, 2022). "Furthermore, CD14CTX express certain molecules associated with immunosuppression such as CXCL8, TGFB1, and IL6, which could be targeted by anti-cancer therapy independently." (PMID 36130508, 2022). "Thus, TGFβ1 may therefore be a provocative target to reverse postoperative immune suppression and prevent cancer recurrence." (PMID 34768810, 2021). "In this context, eHSP90β binds to TGFβ1 forming a complex that, instead of binding TGFβ1 canonical receptors to activate the Smad2/3 signalling pathway, engages the integrin αvβ6 and promotes cancer cell invasion and metastasis through a pathway still undetermined." (PMID 33544155, 2021). "Cancer cells upregulate HBP flux and UDP-GlcNAc levels through increased glucose and glutamine uptake as well as in response to oncogenic-associated signals such as Ras, mammalian target of rapamycin complex 2 (mTORC2), and transforming growth factor beta 1 (TGF-β)." (PMID 31272438, 2019). "However, another study in SLE patient proposed that LDGs arise as a consequence of in situ activation of normal neutrophils, which was confirmed subsequently in a murine model of cancer, wherein NDGs exposed to transforming growth factor beta 1 (TGF-β1) were switched into LDGs." (PMID 31354639, 2019). "Interestingly, GSI treatment decreased both IL-6 and IL-8 expression but not TGFB1 that has been associated with the development of a secretory phenotype of cancer cells." (PMID 31597699, 2019).
cancer (continued). "TGFβ1 was enriched in ovarian cancer-associated fibroblast (CAF)-derived exosomes compared to normal fibroblasts, and CAF-derived exosomes promoted the EMT of cancer cells through the activation of SMAD signaling, which enhanced the migration and invasion ability of these cancer cells." (PMID 31405096, 2019). "However, although Smad2/3 may be absolutely required for TGFβ1-induced EMT in malignant tumors, there are also Smad-independent TGFβ1 pathways involved in EMT." (PMID 30174709, 2018). "Multiple studies have shown that TGFβ1 stimulation can actually induce Hic-5 expression in epithelial cells of different origins, but the exact relationship between Hic-5 function in cancer cells and its link to the TGFβ1- signal transduction pathway remains unclear." (PMID 29137281, 2017). "Therefore, in proof-of-concept experiments, we used TGFβ1 as a model cytokine that could mediate cancer-fibroblast interaction." (PMID 28515430, 2017). "Crude extraction of SGR as well as its pure compounds including astilbin, 5-O-caffeoylshikimic acid and taxifolin, could promote cancer cell apoptosis and block cancer cell adhesion, invasion and migration by inhibiting transforming growth factor beta 1 (TGF-β1) signaling pathway." (PMID 28702078, 2017). "However, in advanced cancer, TGFβ1 is often overexpressed and correlates with worse disease." (PMID 27270652, 2017). "Therefore, we hypothesized that prolonged exposure of cancer cells to TGFβ1 potentially induces DNA methylation and fixes cells in the mesenchymal state." (PMID 27317311, 2016). "However, once the process has started, the activation of latent TGFβ1 might be rapidly amplified through integrin-dependent positive feedback loops; this is likely to happen in both fibrosis and cancer." (PMID 27515461, 2016). "In addition, expression levels of cell cycle (CDK2, CDC2, CCND2) and inflammation markers linked to cancer (NOS2, TGFβ1, CHI3L1 and TFPI) were significantly increased in Caco-2WT/miR-373 compared with Caco-2WT/miR-c, but decreased in Caco-2D299G/α-miR-373 compared with Caco-2D299G/α-miR-c." (PMID 27271572, 2016). "However, potential cancer therapy targeted at TGFB1 remains to be developed." (PMID 26901863, 2016). "Thus, those integrins that activate TGFβ1 can also induce myofibroblast formation and therefore can be considered responsible for myofibroblast-dependent activities that include matrix-remodelling, matrix-stiffening and cancer promotion." (PMID 27515461, 2016). "However, it remains unclear whether LRG modulates the sensitivity of cells to TGFβ1 signaling in cancer." (PMID 25826092, 2015). "Interestingly, TGFβ1 could also up-regulate cancer stem-like cell marker CD44 expression (via Western blot assay)." (PMID 25483103, 2015). "Variations in intracellular calcium, critical events that regulate cancer cell proliferation and progression, may be explained by the complex effects of calcium on different cancer cell signaling pathways, including the Ca-calmodulin protein kinase cascade, Akt, mTOR and TGFβ1." (PMID 24670043, 2014). "Interestingly, genes associated with TGFβ pathway accounted for 10% of directly bounded genes by SMAD3, but many of the pathways affected by TGFβ1/SMAD3 identified using a combination of ChIP-on-Chip and microarray analysis were consistent with the roles of TGFβ in development, fibrosis and cancer." (PMID 21625455, 2011). "These target genes, including IGFBP1, WNT1, WNT10B, TGFB1, PCK1, and SLC2A3, are critical for cancer cell proliferation and metastasis." (PMID 42311859, 2026). "By inhibiting transforming growth factor beta 1 (TGF-β1) and increasing miR-200 expression, UA helps restore the balance that prevents aggressive cancer cell behavior." (PMID 41226811, 2025). "Maximum of the cancers displayed the pattern, with enhanced expression of IL19, TGFβ-1, CXCR4, BMP1, VCAN, and WNT2 protein levels in the samples of KICH, KIRC, LUAD, LUSC especially BRCA when compared to normal samples." (PMID 41348904, 2025).
cancer (continued). "Previous studies have shown that halofuginone inhibits MMP-2 and MMP-9 in cancer and liver tissues, while SIS3 reduces TGFβ1-induced MMP activity in HCC1806 cells." (PMID 40535569, 2025). "Following the same protocol as the immunofluorescence of cancer cells, RAW-Blue macrophages were treated with either TGFβ-1 (4.0 × 10−3 μg/mL), IL-6 (4.1 × 10−5 μg/mL), or HGF (5.97 × 10−4 μg/mL) and stained with E-cadherin, N-cadherin, and vimentin." (PMID 40227834, 2025). "Subsequent analysis also demonstrated a clear relationship between GPX4 expression and key immune checkpoints such as VEGFB, TGFB1, CD276, TNFRSF18, and TNFRSF4 across most cancer types." (PMID 41142608, 2025). "TGFβ1 controls the activities of inflammatory genes like IL-2 and TNF-α, which is a specific way that it links inflammation to cancer." (PMID 39811247, 2025). "Recent studies have highlighted the important role of pro-inflammatory cytokines released after surgical resection, especially TGFβ-1, IL-6, and HGF, in promoting epithelial–mesenchymal transition (EMT) and enhancing cancer cell metastasis potential." (PMID 40227834, 2025). "PTTG1 is capable of inhibiting TGFβ1/SMAD3 signaling and, in turn, suppressing apoptosis and promoting cancer growth." (PMID 40072059, 2025). "SGMS2, a key regulator involved in Cer and sphingolipid homeostasis, promotes EMT mainly by increasing TGF-β1 (transforming growth factor beta 1) secretion to activate the TGF-β/Smad signaling pathway, thereby enhancing cancer cell invasiveness." (PMID 40256431, 2025). "In this study, we explored the prognostic value of DKK3, ECM-1 and TGFB1 using a bioinformatical approach through analysis of large publicly available datasets from The Cancer Genome Atlas Program (TGCA) and Pan-Cancer Atlas databases." (PMID 38855324, 2024). "These non-coding RNAs affect the mRNA levels of Bcl2, TGFβ1, NFκB, VEGF, and matrix metalloproteinase 9 (MMP9), thereby activating corresponding signaling pathways that significantly increase cancer cell metastasis and induce EMT." (PMID 39578849, 2024). "To validate our findings, we recruited a cohort of 21 cancer patients for histological confirmation, revealing significant mRNA upregulation of STAT3, IL6, MMP9, MMP3, TGFB1, VEGF and HIF1A, coupled with downregulation of LHPP and PCK1, PTEN and BLC2." (PMID 39468431, 2024). "In malignant tumors, the polarized M2 macrophages produce and secrete cytokines such as CCL18, CCL20, CCL22, IL10, TGFB1, and GDF15." (PMID 39272860, 2024). "TGFβ1 also induced ITGAV expression in sh-control plastic cancer cells, while this effect was significantly reduced in sh-IGF1R cancer cells." (PMID 39075581, 2024). "Our findings indicated a significant relationship between LOXL2 expression and the majority of the genes in immune checkpoint pathways, like VEGFA, CD276, TGFB1, and IL10 in pan-cancer." (PMID 38922489, 2024). "CAFs have been observed in multiple cancer types and are known to secrete factors (e.g., IL6, IL8, TGFB1) that can regulate cancer proliferation and metastasis." (PMID 38281962, 2024). "The correlation analysis of 24 immunosuppressants indicated that EDNRA was positively correlated with ADORA2A, CSF1R, KDR, TGFB1, and TGFBR1 in cancers, including BLCA, CHOL, ESCA, READ, and STAD." (PMID 39601333, 2024). "Notably, this included TGF-β (TGFB1, TGFB3), drivers of adenosine-mediated immune suppression (NT5E (CD73), ENTPD1 (CD39)), Wnt pathway ligands (WNT7A, WNT4), IL10 and drivers/markers of cancer-associated fibroblast activation (INHBA, WNT7A, TGFB1, FAP, PDGFRA, PDGFRB)." (PMID 39568014, 2024). "Our analysis revealed a positive association between the expression of P2RY6 and immunosuppressive genes such as CD86, CD80, IL2RA, TGFB1, and LGALS9 in pan-cancer." (PMID 37880703, 2023).
cancer (continued). "In this process, a large amount of accumulated lactate can activate TGFβ1/p38 MAPK/MMP2/9 signal axis and stimulate the mitochondrial activity of cancer cells to improve the invasion and metastasis ability of breast cancer cells." (PMID 37582735, 2023). "In line with previous results, TGFB1 is highly expressed in monocytes/macrophages, NK and CD8 + T cells in these cancers." (PMID 37925591, 2023). "Moreover, by adding TGFB1 in the culture medium to simulate the impact of TME-derived TGFB1 on cancer cells, we found that TGFB1 could enhance the invasiveness and cell proliferation of ccRCC cancer cell (786-O cell and ACHN cell) and abrogate the impact of Sunitinib on ccRCC cancer cells." (PMID 37460463, 2023). "In the TME, cancer cell-secreted Lysophosphatidic acid (LPA), TGFβ1, or platelet-derived growth factor (PDGF) can potentially trigger the HIF-1α pathway to cause aerobic glycolysis in the fibroblasts." (PMID 36793444, 2023). "PDCD1, TGFB1, CXCL8, CCL3, CCL4, and CCL5 were highly expressed in subTME-IS; CXCL2 and CXCL12 were highly expressed in subTME-ICI, which was consistent among cancer types." (PMID 38002057, 2023). "An additional intriguing finding in the context of cancer signaling that emerged from the global proteomics analysis is the upregulation of AP‐1 transcription, TGFBR ligand TGFB1 and the CCN family of proteins in ROS1D2113N cells." (PMID 37587872, 2023). "The majority of malignancies have elevated TGFβ1 expression and activation, which encourages epithelial plasticity and can accelerate EMT, a requirement for cancer cell invasion and metastasis." (PMID 37598126, 2023). "Accordingly, PDGFB expression in cancer cells was significantly upregulated by IL6 and TGFB1 in vitro." (PMID 37658364, 2023). "Altogether, our findings provide new mechanistic insights into the molecular machinery of TGFβ1-induced EMT and provide valuable information to better identify cancer cells undergoing EMT in a clinical context." (PMID 36672507, 2023). "This analysis suggested strong involvement of IL1B, TGFB1, and TNF in several cancer hallmarks identified in both bulk and single-cell data of MES." (PMID 37370765, 2023). "Our previous publications suggested that higher levels of cancer cell proliferation, EMT, and motility, as well as the upregulation of TGFβ1 and PI3K/AKT pathways are essential for the development of vessel co-option CRCLM lesion." (PMID 36979711, 2023). "The ARMG risk score showed significantly positive relation with immunoinhibitors TGFB1 and VTCN1, and was negatively related with immunostimulators CD27, CD28, CD40LG, CD80, ENTPD1 and ICOS in pan-cancer." (PMID 38090588, 2023). "Currently, most cancer and fibrotic EMT are regulated by TGFβ1, while TGFβ2 primarily controls EndMT in the heart development, and TGFβ3 mediates EMT in development." (PMID 36882799, 2023). "By analyzing the methylome data of TGFB1 across 9 blood cancer types and healthy controls (GSE28094), we found only small variances of TGFB1 methylation among common blood cancer types and normal samples." (PMID 37925591, 2023). "Studies have focused on TGFβ1 regulation of SOX9 and/or SOX9 regulation of collagen types I and II in processes such as chondrogenesis, cancer, and other types of fibrosis." (PMID 37510994, 2023). "In this study, we have selected and comprehensively evaluated the expression of four commonly known EMT markers (E-cad, N-cad, VIM, TGFβ1), and four unconventional EMT markers (α-SMA, AKR1B1, ITAV, G6PD), less studied in cancer in relation to the EMT process." (PMID 37174052, 2023). "In the present study, our analysis has shown that CD276 expression was positively correlated with a number of immune checkpoint genes, including TGFBR1, TGFB1, NECTIN2, IL10RB and CSF1R, in most types of cancer." (PMID 36717836, 2023).
cancer (continued). "We recently demonstrated the upregulation of EMT and motility biomarkers in the cancer cells of vessel co-opting CRCLM lesions, which correlated with the upregulation of transforming growth factor beta 1 (TGFβ1) in their proximate liver parenchyma." (PMID 35267627, 2022). "Gene expression profiling provided further evidence for pEMT of TGFβ1-treated organoids and showed that their transcriptomes resemble those of human poor prognosis CMS4 cancers which likewise exhibit pEMT features." (PMID 35075245, 2022). "Several of these specialized TME microenvironments are enriched by the pan-cancer survival network, for example HIF1A signaling (p = 4.27 × 10−6; FGF2, IGF2, MMP1, MMP14, MMP3, PIK3R3, SERPINE1, TGFB1)." (PMID 35106465, 2022). "Thus, TGFB1 blockades have been considered to have great promise for enhanced antitumor activity; hence, anti-TGFB1 therapeutics, such as antisense oligonucleotide-, ligand-, and receptor-targeted neutralizing antibodies, and small molecule inhibitors were broadly tested in different cancer types." (PMID 36425786, 2022). "To further validate the link between CD93 expression and other cancer-related biological functions in pan-cancer, we analyzed additional two biological roles of CD93 in various human tumors including autophagy, EMT, TGFB1, and Wnt pathway." (PMID 35242761, 2022). "The data provided here is a comparison of a normal and a cancer cell line in response to the following growth factors, EGF, TGFα, TGFβ-1, VEGF, and NGF, and a specific inhibitor of Akt, MK2206." (PMID 35681586, 2022). "The conditioned media of cocultured IHH hepatocytes with cancer (LS174, SW620 or HT29) cells showed a higher abundance of TGFβ1 compared to the control." (PMID 35267627, 2022). "We found ENPEP is correlated with TGF‐β coding genes TGFB1(80%), TGFB2(64%), TGFB3(88%) in most cancers." (PMID 34862755, 2022). "As TGFβ1, TEV enriched in IL-10 were detected in plasma of different cancer patients; however, the most relevant action performed by TEV is the induction of IL-10 and TFGβ1 in target cells via their RNA content." (PMID 36011012, 2022). "Co-culture with M2 macrophages significantly upregulated TGFβ1, N-cadherin, and vimentin in MDA-MB-231 and MCF7 cancer cells." (PMID 35955525, 2022). "Our study suggests that cancer cells stimulate apoptosis and EMT in hepatocytes through the overexpression of TGFβ1." (PMID 35267627, 2022). "It is essential to note that TGFB1, which is an effector of immune suppression, showed strong positive correlations with RCN3 expression levels in the vast majority of TCGA cancer types." (PMID 35651805, 2022). "Lactate-activated macrophages secrete TGFβ1, which is responsible for the production of CCR5 (the CCL5 receptor) in cancer cells (MCF-7) and activation of the EMT program." (PMID 35054987, 2022). "Increased frequencies of LAG3+ Tregs were found in the PBMCs of cancer patients, which expand in the TME to secrete IL-10 and transforming growth factor beta 1 (TGF-β1)." (PMID 35345849, 2022). "Upon treatment with TGFβ1, organoids adopted a transcriptional profile highly similar to the transcriptome of CMS4 cancers which are characterized by TGFβ pathway activation, mesenchymal features, high stromal content, and particularly poor prognosis." (PMID 35075245, 2022). "TGFB1 overexpression in GBC has been correlated with advanced stage and poor patient survival and reported to promote cancer cell proliferation migration and invasion." (PMID 36505879, 2022). "Not only that, in the two cancers, the most significant correlation difference was the TGF-β gene (TGFB1, TGFB3)." (PMID 36207751, 2022). "TGFβ1 secretion mediated an increase in invasive and metastasizing abilities of MCF7 and MDA-MB-231 cancer cells when co-cultured with M2 macrophages." (PMID 35955525, 2022).